SORD (sorbitol dehydrogenase)
Description:
Polyol dehydrogenase that catalyzes the reversible NAD(+)- dependent oxidation of various sugar alcohols. Is mostly active with D-sorbitol (D-glucitol), L-threitol, xylitol and ribitol as substrates, leading to the C2-oxidized products D-fructose, L-erythrulose, D-xylulose, and D-ribulose, respectively. Is a key enzyme in the polyol pathway that interconverts glucose and fructose via sorbitol, which constitutes an important alternate route for glucose metabolism. The polyol pathway is believed to be involved in the etiology of diabetic complications, such as diabetic neuropathy and retinopathy, induced by hyperglycemia. May play a role in sperm motility by using sorbitol as an alternative energy source for sperm motility. May have a more general function in the metabolism of secondary alcohols since it also catalyzes the stereospecific oxidation of (2R,3R)-2,3-butanediol. To a lesser extent, can also oxidize L-arabinitol, galactitol and D-mannitol and glycerol in vitro. Oxidizes neither ethanol nor other primary alcohols. Cannot use NADP(+) as the electron acceptor.
Synonyms: SDH; RDH; XDH; HEL-S-95n; HMNR8; SORD1; SORDD
Tractability: Small molecule: a structure with a bound ligand is known; it has a high-quality binding pocket; it belongs to a druggable protein family. Antibody: UniProt places it where antibodies can reach, with medium confidence. PROTAC: ubiquitination databases record sites on it; its protein half-life has been measured; a small molecule that binds it is known.
Target class: Enzyme; Oxidoreductase
Gene: Protein-coding gene on chromosome 15 (45,023,147 to 45,077,185, forward strand). Ensembl gene ENSG00000140263.
Subcellular location: Mitochondrion membrane; Cell projection, cilium, flagellum
Subcellular location (Human Protein Atlas): Cytosol; Acrosome; Equatorial segment
Pathways (Reactome):
Metabolism: Formation of xylulose-5-phosphate; Fructose biosynthesis
Gene Ontology:
Molecular function: (R,R)-butanediol dehydrogenase activity; D-xylulose reductase activity; identical protein binding; L-iditol 2-dehydrogenase (NAD+) activity; NAD binding; ribitol 2-dehydrogenase (NAD+) activity; zinc ion binding; carbohydrate binding; alcohol dehydrogenase (NAD+) activity; oxidoreductase activity; oxidoreductase activity, acting on the CH-OH group of donors, NAD or NADP as acceptor
Biological process: fructose biosynthetic process; sorbitol catabolic process; xylitol catabolic process; xylitol metabolic process; flagellated sperm motility; glucose metabolic process
Cellular component: extracellular exosome; membrane; cytosol; extracellular region; mitochondrial membrane; motile cilium; mitochondrion
Genetic constraint (gnomAD): Loss-of-function variants: 11 observed, 19.6 expected, observed/expected ratio (o/e) 0.56, 90% interval 0.35 to 0.93. The upper end of that interval is the gene's LOEUF score, 0.93, which puts it in group 3 of 6, group 1 being the genes least tolerant of losing a copy. Missense variants: 220 observed, 249.97 expected, observed/expected ratio (o/e) 0.88, 90% interval 0.79 to 0.98. Synonymous variants: 94 observed, 98.36 expected, observed/expected ratio (o/e) 0.96, 90% interval 0.81 to 1.13.
Gene-disease validity (ClinGen):
ClinGen rates the evidence that SORD causes each of these diseases.
Charcot-Marie-Tooth disease (autosomal recessive): Definitive. An inherited degenerative disorder involving the peripheral nerves.
Homologues: Orthologues: chimpanzee SORD (98% identical), macaque SORD (96% identical), guinea pig SORD (88% identical), rabbit SORD (88% identical), pig SORD (85% identical), mouse Sord (83% identical), rat Sord (82% identical), tropical clawed frog sord (78% identical), zebrafish sord (76% identical), Drosophila melanogaster Sodh1 (55% identical), Drosophila melanogaster Sodh2 (55% identical), Caenorhabditis elegans R04B5.5 (52% identical), and 1 more. Paralogues in human: ADH1A (22% identical), ADH1B (22% identical), ADH1C (22% identical), CRYZ (22% identical), VAT1 (21% identical), ADH5 (21% identical), VAT1L (20% identical), ADH4 (20% identical), ADH7 (20% identical), ADH6 (20% identical), RTN4IP1 (20% identical), TP53I3 (20% identical), and 5 more.
Diseases named in the same sentence as SORD in open-access papers:
SORD is named in the same sentence as 62 diseases in open-access papers, as found by Europe PMC text mining. Sharing a sentence is not in itself a finding about the gene and the disease. The quoted sentences say what the papers report.
diabetes (13 papers, 2008 to 2026). "Sorbitol dehydrogenase mutations have been shown to cause secondary complications of diabetes, which are known predisposing or confounding factors to PE." (PMID 30941163, 2019). "The activation of polyol pathway enzymes aldose reductase and sorbitol dehydrogenase plays a crucial role in the microvascular complications of diabetes." (PMID 37237843, 2023). "Its flavonoids, tannins, and polyphenols have anti-inflammatory and antioxidant properties inhibiting aldose reductase and sorbitol dehydrogenase pathways, alleviating the cataractogenic and retinopathic complications of diabetes." (PMID 38067127, 2023). "Hyperglycemia in patients suffering from diabetes trains the polyol pathway, so that glucose is converted to sorbitol and fructose due to aldose reductase enzyme and sorbitol dehydrogenase." (PMID 31915735, 2019). "We show here that flux via aldose reductase and sorbitol dehydrogenase continues to increase with duration of diabetes in the BBZ rat hearts." (PMID 18957123, 2008). "In addition, hyperglycemic and hypertonic conditions in diabetes are known to stimulate aldolase reductase, which given the expression of sorbitol dehydrogenase in PT would increase the flux of fructose into metabolic routes." (PMID 38474316, 2024). "This is consistent with findings that sorbitol dehydrogenase inhibitors fail to increase nerve blood flow or conduction velocity in experimental diabetes but instead worsen nerve energy status in some studies, and apparently exacerbate sympathetic autonomic neuropathy in STZ-induced diabetes." (PMID 25512003, 2015).
Hyperglycemia (12 papers, 2008 to 2025). An increased concentration of glucose in the blood. "Hyperglycemia also causes increased conversion of glucose to sorbitol and fructose via the polyol pathway and overexpression of enzymes, which are part of this pathway: aldose reductase (AR) and sorbitol dehydrogenase (SDH)." (PMID 38202299, 2024). "It is well known that hyperglycaemia increases the rates of glucose metabolism via glycolysis and the SORD gene pathway, but the importance of SORD downregulation and its contribution to oxidative stress and diabetic complications in human in vivo and vitro models remains unclear." (PMID 28676096, 2017). "Furthermore, the increases in protein expression of aldose reductase and sorbitol dehydrogenase coupled with increased hyperglycemia presented here may, in part, be responsible for the increased flux via these enzymes in 48 weeks diabetic BBZ rat hearts." (PMID 18957123, 2008). "As regards kidney tissues, a chronic status of hyperglycemia could elicit cellular damage by making use of the polyol pathway; glucose is converted to sorbitol by aldose reductase using NADPH, sorbitol should be converted to fructose by sorbitol dehydrogenase which is deficient in kidney." (PMID 39905472, 2025). "More importantly, hyperglycemia-induced phosphorylation of YWHAH was almost completely attenuated by silencing AKR1B1 and/or SORD, strongly suggesting that polyol pathway-derived fructose drives S25 phosphorylation of YWHAH." (PMID 38200154, 2024). "The recruitment of SLUG to the CDH1 promoter was augmented by hyperglycemia, which was attenuated by silencing AKR1B1 and/or SORD." (PMID 38200154, 2024). "Moreover, hyperglycemia-induced cytoskeletal rearrangement and CDH1 suppression were attenuated by AKR1B1 and/or SORD knockdown." (PMID 38200154, 2024). "When SORD activity is low or absent in the liver, sorbitol can accumulate in hepatocytes during hyperglycemia." (PMID 34885252, 2021). "Exposure to iAs also increased SORD (sorbitol dehydrogenase), TKFC (transketolase-like protein 1), and KHK (ketohexokinase) expression in the liver, leading to increased hepatic glucose production via the polyol pathway, ultimately contributing to hyperglycemia in mice." (PMID 37886432, 2023). "Therefore, the early stages of hyperglycemia do not necessitate an increase in sorbitol dehydrogenase levels." (PMID 30470798, 2018).
neuropathy (12 papers, 2020 to 2025). A disorder affecting the nervous system that manifests with pain, tingling, numbness, and/or muscle weakness. "In our group 1 case, the diagnosis of SORD deficiency that was complicated by the paucity of SORD genes on commercial neuropathy panels and quantitative sorbitol analysis." (PMID 39543639, 2024). "His variants in SORD are reported to be the most common cause of SORD deficiency and subsequently the most common cause of recessive neuropathy." (PMID 39543639, 2024). "Mutations in SORD have been described as the most frequent cause of recessive inherited neuropathies in many studies." (PMID 36431311, 2022). "The eighteen patients we detected with biallelic SORD variants account for 0.78% (18 patients out of 2313) of all diagnosed patients and 1.36% of all families for which the cause of their neuropathy had been stated (16 families from 1171)." (PMID 33875678, 2021). "Similarly, pathogenic variants in the SORD gene were recently identified as the most common recessive inherited neuropathy." (PMID 35330153, 2022). "Importantly, we demonstrated mitochondrial dysfunction as a critical mechanism underlying SORD deficiency–induced neuropathy, evidenced by increased ROS levels, increased levels of apoptosis, compromised ATP production, and the decreased intensity of mitochondrial marker TOM20." (PMID 37014713, 2023). "The SORD neuropathy is caused by biallelic mutations to the gene SORD, encoding sorbitol dehydrogenase, leading to the arrest of the polyol pathway and the development of a peripheral neuropathy." (PMID 38796985, 2024). "Sorbitol dehydrogenase (SORD), which converts sorbitol to fructose in the polyol pathway, is closely related to various diabetic complications (viz., neuropathy, retinopathy, cataracts, and nephropathy)." (PMID 33321873, 2020). "Another challenge that lays ahead is to integrate the pathways identified through human disease cohorts into known signaling pathways mediating axon degeneration (for example, are processes disrupted by new neuropathy genes like SORD or COA7 upstream or downstream of Sarm1)?" (PMID 37614471, 2023). "Sorbitol dehydrogenase (SORD) catalyzes the conversion of sorbitol into fructose within the metabolic pathway, which is crucial because sorbitol can play a role in certain pathological conditions, such as neuropathy and autosomal distal hereditary motor disorder." (PMID 40041500, 2025). "Drosophila has two functional SORD proteins that are 75 and 73% identical to the human SORD protein, and Drosophila melanogaster models of SORD deficiency could not fully mimic the pathogenesis of SORD-related neuropathy, especially sensory nerve impairment." (PMID 34819907, 2021).
diabetic neuropathy (7 papers, 2018 to 2025). A chronic, pathological complication associated with diabetes mellitus, where nerve damages are incurred due to diabetic microvascular injury involving small blood vessels that supply these nerves, resulting in peripheral and/or autonomic nerve dysfunction. "The initial step is the conversion of glucose to sorbitol by aldose reductase, followed by sorbitol dehydrogenase catalyzes sorbitol into fructose, which has been implicated in the pathophysiology of preclinical models of diabetic neuropathy." (PMID 38915017, 2024). "For example, AKR1B1 and SORD have been proven to be associated with the occurrence of complications such as diabetic neuropathy." (PMID 33953784, 2021). "SORD is an important enzyme that converts sorbitol to fructose in the two-step polyol pathway previously implicated in diabetic neuropathy." (PMID 34819907, 2021). "Furthermore, humans with sorbitol dehydrogenase deficiencies have an increased propensity for diabetic neuropathy." (PMID 39386468, 2024). "We assessed changes in gene expression of sorbitol dehydrogenase (SORD) and aldose reductase (AKR1B1) as an indirect measure of polyol pathway flux and, along with protein kinase C (PKD2), as key characteristic markers for diabetic neuropathy." (PMID 30470798, 2018).
distal hereditary motor neuropathy (5 papers, 2021 to 2024). "Our recent study and others also identified SORD mutations as the most common genetic cause of autosomal recessive distal hereditary motor neuropathy/CMT2 (dHMN/CMT2)." (PMID 37014713, 2023). "Recently a juvenile ALS patient was reported carrying the c.757delG mutation of the sorbitol dehydrogenase (SORD) gene, which was also a related mutation of Charcot-Marie-Tooth disease (CMT) and distal hereditary motor neuropathy (dHMN)." (PMID 36431311, 2022). "Biallelic mutations in the sorbitol dehydrogenase (SORD) gene have recently been found to be one of the most frequent causes of autosomal recessive axonal Charcot-Marie-Tooth (CMT2) and distal hereditary motor neuropathy (dHMN)." (PMID 34819907, 2021).
Charcot-Marie-Tooth disease (4 papers, 2021 to 2025). "Mutations in sorbitol dehydrogenase cause the most common recessive form of Charcot-Marie-Tooth disease, CMT-SORD." (PMID 39938083, 2025). "Biallelic loss-of-function mutations in the sorbitol dehydrogenase (SORD) gene cause the most common recessive type of Charcot-Marie-Tooth disease (CMT), CMT-SORD." (PMID 39938083, 2025). "Mutations in SORD cause a subset of Charcot-Marie-Tooth disease, a hereditary neuropathy." (PMID 34970554, 2021).
prostate carcinoma (4 papers, 2014 to 2021). A carcinoma that arises from epithelial cells of the prostate gland. "Two studies demonstrated that SORD is an androgen-regulated gene in prostate cancer." (PMID 34249670, 2021). "The eight proteins highlighted in this study (KLK3, SORD, SPON2, IMPDH2, ACTN4, ATP1B1, HSPB1, and KHDRBS1) represent a signature associated with AR modulation during the transition from androgen-dependent to castration-resistant prostate cancers." (PMID 29966326, 2018). "Sorbitol was catalyzed by sorbitol dehydrogenase (SORD) whose expression was regulated by androgens, which were essential for the development of prostate cancer." (PMID 25153931, 2014).
fatty liver disease (3 papers, 2021 to 2025). A reversible condition wherein large vacuoles of triglyceride fat accumulate in liver cells via the process of steatosis. "The interactions between saroglitazar and ferulic acid with different enzymes and metabolites involved in metabolic dysfunction-associated fatty liver disease (MASLD), such as SORD, HK1, HK2, MgATP, KHK, HK3, ALDOB, ALDOC, and fructose-1-phosphate (F1P)." (PMID 40130107, 2025).
lung carcinoma (3 papers, 2023 to 2025). "Recent evidence of endogenous erythritol synthesis in human blood, and in A549 lung cancer cells by the reductases ADH and SORD, casts doubt on the view that polyols are not endogenously produced in humans." (PMID 40161620, 2025).
autosomal recessive dHMN (2 papers, 2022 to 2023). "This study supports the hypothesis that the specific SORD mutation (c.757delG) is the most common cause of childhood-onset mild form of the autosomal recessive dHMN." (PMID 35436891, 2022).
diabetic retinopathy (2 papers, 2021 to 2024). "Inhibiting key enzymes in this pathway, aldose reductase (AR) and sorbitol dehydrogenase (SD), alongside preventing AGE formation, may offer therapeutic strategies for diabetic retinopathy and other vascular complications." (PMID 39764459, 2024).
liver disease (2 papers, 2012 to 2015). "More recent guidelines for diagnosing liver disease in manatees focus on measuring sorbitol dehydrogenase, glutamate dehydrogenase, and tracking bilirubin levels." (PMID 22984521, 2012). "For this purpose, various serum biomarkers have been proposed, such as alanine aminotransferase (ALT), sorbitol dehydrogenase (SDH), glutathione S-transferase (GSTα), GLDH, microRNAs, CK-18, and HMGB-1, but these are not specific of DILI or liver disease." (PMID 26824035, 2015).
Alzheimer disease (1 paper, 2022). A progressive, neurodegenerative disease characterized by loss of function and death of nerve cells in several areas of the brain leading to loss of cognitive function such as memory and language. "In addition, the SORD gene was also proposed as a biomarker candidate gene for another neurodegenerative disease, Alzheimer’s disease (AD), since it is commonly dysregulated between AD blood and brain tissues." (PMID 36431311, 2022).
autosomal dominant-dHMN (1 paper, 2020). "Mutations in genes encoding aminoamide tRNA synthetase (ARS) might be a frequent cause of autosomal dominant-dHMN, and SORD mutation might account for a majority of autosomal recessive-dHMN cases." (PMID 33381078, 2020).
axonal neuropathy (1 paper, 2022). Any nerve disorder affecting the axon of a nerve. "Sorbitol is not only an osmotic stressor but also an oxidative stressor through its sorbitol dehydrogenase reaction, playing a role in the pathogenesis of axonal neuropathy and diabetic peripheral neuropathy." (PMID 36431311, 2022).
Azoospermia (1 paper, 2022). Absence of any measurable level of sperm,whereby spermatozoa cannot be observed even after centrifugation of the semen pellet. "In non-obstructive azoospermia, we show that the genes pyruvate dehydrogenase phosphatase regulatory (PDPR) and sorbitol dehydrogenase regulatory (SORD) were decreased (downregulated)." (PMID 36293429, 2022).
colorectal adenoma (1 paper, 2019). An adenoma that arises from the colon or rectum. "SORD expression and activity was upregulation in colorectal adenomas whereas SORD knockdown significantly blocked epithelial-to-mesenchymal transition (EMT)." (PMID 31272500, 2019).
colorectal neoplasm (1 paper, 2020). A benign or malignant neoplasm that affects the colon or rectum. "In addition to the findings by Schwab and coworkers showing the association between SORD expression and EMT, Uzozie and colleagues analyzed SORD overexpression in precancerous colorectal neoplasms." (PMID 33302403, 2020).
coronary artery disease (1 paper, 2024). "Studies have indicated SORD’s involvement as a cuproptosis-related gene in coronary artery disease." (PMID 39050579, 2024).
epilepsy (1 paper, 2025). A brain disorder characterized by episodes of abnormally increased neuronal discharge resulting in transient episodes of sensory or motor neurological dysfunction, or psychic dysfunction. "A neurologic comorbidity was reported in six patients, including epilepsy, multiple sclerosis, subarachnoid haemorrhage, intellectual disability, stroke and Kennedy disease, which were all considered unlikely to be related to SORD mutations." (PMID 39938083, 2025).
gastric cancer (1 paper, 2024). A primary or metastatic malignant neoplasm involving the stomach. "Two enzymes, AKR1B1 and SORD, in the polyol pathway were analyzed in human gastric cancer tissues." (PMID 38200154, 2024). "Of the three CDH1 repressors SNAIL, SLUG, and TWIST, YWHAH robustly interacted with SLUG in gastric cancer cells, which was inhibited by silencing AKR1B1 and/or SORD." (PMID 38200154, 2024). "A chi-square analysis revealed that gastric cancers with elevated expression of both AKR1B1 and SORD are more aggressive." (PMID 38200154, 2024).
glioma (1 paper, 2021). A benign or malignant brain and spinal cord tumor that arises from glial cells (astrocytes, oligodendrocytes, ependymal cells). "The present study was novel in building a uronic acid metabolic process–related signature involving five genes (UGT8, DCXR, SORD, XYLB, and CRYL1) to predict the survival of glioma in the CGGA database." (PMID 33324981, 2021).